RN7SL82P (RNA, 7SL, cytoplasmic 82, pseudogene)
Gene: Miscellaneous RNA gene on chromosome 15 (30,800,160 to 30,800,396, forward strand). Ensembl gene ENSG00000278696.
Homologues: Orthologues: pig Metazoa_SRP (59% identical). Paralogues in human: RN7SL628P (100% identical), RN7SL469P (99% identical), RN7SL673P (99% identical), RN7SL719P (99% identical), RN7SL495P (99% identical), RN7SL196P (98% identical), RN7SL286P (98% identical), RN7SL539P (98% identical), RN7SL185P (97% identical), RN7SL796P (97% identical), Metazoa_SRP (92% identical), RN7SL106P (92% identical), and 707 more.